AIM2 (absent in melanoma 2)
Diseases named in the same sentence as AIM2 in open-access papers (continued):
Sharing a sentence is not in itself a finding about the gene and the disease.
lupus (continued). "Selective pharmacological JAK1 inhibition significantly reduces the expression of typical proinflammatory mediators such as CXCL chemokines, BLyS, TRAIL, and AIM2 in CLE in vitro models and also improves skin lesions in lupus-prone TREX1–/– -mice markedly." (PMID 32194562, 2020). "Considering the antagonizing relationship of IFI16 and AIM2, how AIM2 and IFI16 work in lupus is worthy of further investigation." (PMID 31427885, 2019). "Inhibition of AIM2 promoted the expression of another IFI member IFI16/p202, which was found increased in leukocytes of lesion skin and peripheral blood from lupus patients." (PMID 31427885, 2019). "Evidence supports a role of AIM2, IFI16, and the regulatory p202 proteins (p202a and p202b) in the pathogenesis of Sjogren’s syndrome and systemic lupus erythematosus (SLE)." (PMID 24367371, 2013). "Moreover, AIM2 and IFI16 filaments also persist and are even stigmatized as autoantigens in debilitating autoimmune disorders such as systemic lupus erythematosus and Sjögren’s syndrome." (PMID 38252125, 2024). "Furthermore, AIM2 was shown to bind neutrophil extracellular traps, leading to DNase resistant nucleoprotein fibers that can serve as autoantigens in systemic lupus erythematosus (SLE)." (PMID 38918243, 2024). "Furthermore, patients with DLE (a subtype of cutaneous lupus erythematosus) whose main manifestation was skin lesions, displayed much more increased AIM2 levels than patients with SLE, suggesting the clinical implication of AIM2, particularly in skin lesion features of lupus patients." (PMID 35343082, 2022). "Importantly, conditional knockout of Aim2 in B cells attenuates lupus symptoms and reduces TFH, GC B cells and plasma cells in the pristane‐induced lupus model." (PMID 35538881, 2022). "To confirm our hypothesis of Aim2‐TFH function in SLE, we therefore induced a cGVHD lupus model by transferring CD8+ T‐cell‐depleted lymphocytes from Aim2‐/‐ or WT mice to B6D2F1 recipient mice." (PMID 35343082, 2022). "AIM2 expression is closely correlated with macrophage activation, and inhibition of AIM2 expression significantly ameliorates SLE syndrome in apopDNA-induced, lupus-affected mice." (PMID 32528469, 2020). "The expression of AIM2, another inflammasome sensing double-stranded nucleic acids in the cytoplasm, was positively correlated with disease severity in patients with SLE and lupus-prone mouse model." (PMID 31871956, 2019). "Moreover, the critical cytokine of lupus, IFN-α, can influence expression/activity of both AIM2 and IFI16." (PMID 31427885, 2019). "Patients with systemic lupus erythematosus (SLE) suffer from disordered Th1/Th2 and Treg/Th17 balances, evidence has demonstrated that NLRP3, NLRP1, NLRC4, and AIM2 were involved in the regulation of Th1, Tfh, and Th17 cell-mediated immune responses." (PMID 38177104, 2024). "In the context of autoimmune diseases, such as systemic lupus erythematosus (SLE), rheumatoid arthritis (RA), and Sjögren’s syndrome (SS), dysregulated hyperactivation of the AIM2 inflammasome pathway may occur due to the continuous accumulation of self-derived DNA substrates." (PMID 39100670, 2024). "In summary, our immunostaining experiments provide evidence that AIM2 and IFI16 bind NETs in the setting of diffuse proliferative lupus nephritis, establishing AIM2 and IFI16 as NET-bound SLE autoantigens." (PMID 35608258, 2022). "The expression of Absent in melanoma 2 (human AIM2 and murine Aim2) is found to be increased in TFH‐like cells (CD4+Bcl6+PD1+) in the peripheral blood and skin lesions of lupus patients, compared to healthy controls." (PMID 35538881, 2022). "Here, our findings demonstrated that high AIM2 expression upregulates the TFH cell response and that the IL‐21‐AIM2‐TET2‐c‐MAF pathway contributes to autoimmune progression during lupus development, which may facilitate new clinical therapeutics targeting AIM2 in T cells for the treatment of SLE." (PMID 35343082, 2022).
colorectal cancer (39 papers, 2015 to 2026). A primary or metastatic malignant neoplasm that affects the colon or rectum. "Deficiencies in AIM2 result in pathological RPE-EMT, which is consistent with EMT observed in hepatocellular or colorectal carcinoma cells in AIM2-deficient patients." (PMID 39870644, 2025). "In colorectal cancer, a high frequency of missense and frameshift mutation in AIM2 has been detected." (PMID 36932407, 2023). "At the same time, previous studies have found that the loss of AIM2 expression has a close relationship with the low survival rate of patients with colorectal cancer." (PMID 36248785, 2022). "Host genetic factors and gut microbiota also had a synergistic effect on the susceptibility to colorectal cancer in AIM2-deficient mice." (PMID 34571825, 2021). "It has also been reported that AIM2 deficiency in a AOM/DSS mouse model of colorectal cancer resulted in an increase in tumor load in an inflammasome-independent manner (Akt activation) and was mediated by a non–bone marrow source of AIM2." (PMID 34571825, 2021). "It was also reported that AIM2 had a high frequency of frameshift mutations in gastric, endometrial and colorectal cancers." (PMID 27167192, 2016). "Furthermore, AIM2 played an protumor role in colorectal tumors because overexpression of AIM2 in colorectal cancer cells induced the expression of invasion‐associated genes such as VIM and MCAM." (PMID 35070978, 2021). "Moreover, several studies have demonstrated that loss of AIM2 expression exhibits oncogenic properties in colorectal cancer and low levels of AIM2 predict poor survival in colorectal cancer patients." (PMID 33859277, 2021). "The reduction of AIM2 expression is linked to a poorer prognosis in colorectal cancer patients." (PMID 32121297, 2020). "Indeed, loss-of-function mutations in AIM2 are present in more than half of the tumors from patients with bowel cancers, including colorectal cancers." (PMID 31786265, 2020). "Extensive research has been published on AIM2 in colorectal cancer, although it is known to also function in many other cancers." (PMID 41811896, 2026). "AIM2 was initially identified as a tumor suppressor gene in murine models of colorectal cancer; however, other studies revealed that AIM2 also participates in innate immune signaling as a cytosolic DNA sensor and a key regulator of inflammasome activation." (PMID 41369412, 2025). "In the murine AOM/DSS model of colorectal cancer, AIM2 was found to suppress AKT activation through interaction with DNA-dependent protein kinase to control tumor development and suppress intestinal stem cell proliferation." (PMID 38918243, 2024). "An omics study involving single-cell analysis showed the overall survival of colorectal cancer patients with low AIM2 was significantly lower than that in the group with high AIM2 expression." (PMID 39290706, 2024). "Our previous investigation unveiled the intricate mechanism by which AIM2 inhibits colorectal cancer by regulating intestinal stem cell activity and inducing changes in gut microbiota." (PMID 38918243, 2024). "For instance, two independent studies on colorectal cancer have shown that AIM2 regulates tumor development through inflammasome-independent pathways." (PMID 38429284, 2024). "Case reports have shown significantly decreased the expression levels of NLRP1, NLRP3, NLRC4, AIM2, and other inflammasomes in patients with colorectal cancer compared to healthy controls." (PMID 38756775, 2024). "In patients with colorectal cancer with low AIM2 expression, the PI3K–AKT signaling pathway is upregulated, which increases the proliferative and survival abilities of the cancer cells, making them highly malignant." (PMID 37046775, 2023). "Survival analysis suggested that the OS of colorectal cancer patients in the low AIM2 group was significantly lower than that in the high expression group (P=0.036), which was consistent with our analysis and previous reports." (PMID 36248785, 2022).
colorectal cancer (continued). "We examined the expression of AIM2 in 114 pairs of colorectal cancers versus paracancerous using immunohistochemistry and showed that AIM2 was significantly low expressed in colorectal cancers (P=0.026)." (PMID 36248785, 2022). "The authors also reported that the reduction in NLRC3 and AIM2 mRNA expression in colorectal cancer cells was correlated with the progression of colorectal cancer." (PMID 34571825, 2021). "They found that the mRNA expression of NLRC3 as an inflammation checkpoint; NLRP1, NLRP3 and NLRC4 as the components of inflammasome and AIM2 were all decreased in colorectal cancer." (PMID 34571825, 2021). "AIM2 inflammasome activation impaired cell invasion and metastasis via inhibiting Akt pathway in colorectal cancer." (PMID 32725966, 2020). "Reduced expression and instability of the AIM2 have been reported in cancer tissues from patients with colorectal cancer." (PMID 32121297, 2020). "On the other hand, AIM2 has been shown to suppress the development of cancer such as colorectal cancer." (PMID 32121297, 2020). "On the other hand, restoration of AIM2 has been shown to stimulate invasion of colorectal cancer cells." (PMID 28526809, 2017). "The comparatively high prevalence of HT001 and AIM2 mutations in MMR-DCF is also interesting with regard to frameshift peptide vaccination approaches, which are currently evaluated in MSI-H colorectal cancer patients." (PMID 25816162, 2015). "AIM2 reduced Akt activation and tumor burden in colorectal cancer models, while an Akt inhibitor reduced tumor load in Aim2−/− mice." (PMID 26378020, 2015). "However, AIM2 also has inflammasome‐independent roles, specifically in the setting of colitis and colorectal cancer, where AIM2 attenuates colon cancer development by regulating stem cell proliferation, primarily by inhibiting excessive AKT activation." (PMID 39425547, 2025). "It was found that due to the suppressive effect of AIM2 on colorectal cancer, the AIM2 inflammasome plays a role in preventing the development of this cancer (AIM2 effect in DNA-dependent activation of Akt regulating epithelial cell proliferation via protein kinase)." (PMID 39290706, 2024). "In addition, it has also been reported that AIM2 regulate the development of colorectal cancer and host defense against Salmonella infection in inflammasome-independent manner." (PMID 38918243, 2024). "Lack of AIM2 is associated with increased mortality in colorectal cancer patients and promoted colorectal tumorigenesis in Aim2-deficient mice." (PMID 36932407, 2023). "In addition, research using a colon cancer mouse model revealed that low AIM2 expression induced an imbalance of the intestinal flora (dysbiosis), thereby providing a suitable environment for the proliferation of colorectal cancer cells." (PMID 37046775, 2023). "For instance, AIM2 has long been known as a marker for poor prognosis in colorectal cancer." (PMID 37046775, 2023). "Therefore, NLR and AIM2 genes can be used as biomarkers of colorectal cancer and cancer progression." (PMID 34571825, 2021). "AIM2 reduces the proliferation of colorectal cancer cells by inducing cell cycle arrest." (PMID 34680930, 2021). "On the contrary, AIM2 gene is required to restrain the progression of colon cancer through an inflammasome-independent manner, proliferation control of intestinal stem cells, and the regulation of gut microbiota, suggesting that AIM2 gene plays a protective role in colorectal cancer." (PMID 36118867, 2022). "For instance, studies had revealed that the overexpression of AIM2 inflammasome exhibited antitumour effects in hepatocellular cancer, and decreased expression or absence of AIM2 may cause colorectal carcinoma." (PMID 35233921, 2022). "Therefore, AIM2 modulation could be applied as a therapeutic approach for preventing colorectal cancer." (PMID 34571825, 2021).
colorectal cancer (continued). "Absent in melanoma 2 (AIM2), a DNA sensor that plays an important role in natural immunity system, has been reported to participate in colorectal cancer (CRC) development." (PMID 33842454, 2021). "A recent study demonstrated a proapoptotic and antiproliferative effect of AIM2, and further suggested that this is antagonized by the prosurvival phosphatidylinositol-3-kinase (PI3K)/protein kinase B (Akt) pathway in colorectal cancer cells." (PMID 31786265, 2020). "Since inflammation is a central component of colorectal cancer (CRC), this work was undertaken to analyze NLR and AIM2 expression in human CRC by combining bioinformatics analysis and experimental verification using clinical tissue samples." (PMID 26378020, 2015). "In colorectal cancer patients, a reduced or absent AIM2 expression correlated with an up to 3-times rise in overall mortality compared to cancer patients with unaltered AIM2 expression." (PMID 40356602, 2025). "AIM2 upregulation has been correlated with a good prognosis and suppresses epithelial–mesenchymal transition (EMT) via modulating PI3K/Akt and inflammasome pathways in colorectal cancer." (PMID 38166970, 2024). "AIM2 was decreased in ~67.4% of colorectal cancer (CRC) cells and was directly absent in 9.18% of CRC cells." (PMID 37061535, 2023). "In colorectal cancer AIM2 appears to play a protective role as lack of AIM2 expression is associated with cancer progression, metastasis, and less favorable prognosis." (PMID 28526809, 2017). "Several studies have demonstrated that a lack of AIM2 expression may be utilized as a biomarker for identifying colorectal cancer patients with poor prognosis." (PMID 33859277, 2021). "However, in colorectal cancer, the inflammasome-independent effect of AIM2, primarily mediated by a non-bone marrow source of AIM2, may result in the suppression of colon tumorigenesis." (PMID 35682857, 2022). "Also AIM2 (absent in melanoma 2), and the pro-apoptotic BAX (BCL2-associated X protein) are inactivated by coding microsatellite mutations in the majority of MSI-H colorectal cancer." (PMID 25816162, 2015). "They identified ISG15 among the 111 transcripts that were upregulated by AIM2, compared with expression levels in AIM2-negative HCT116 cells, and reported a positive correlation between the expression of ISG15 and AIM2 in ten different IFN-γ-treated colorectal cancer cell lines." (PMID 27626310, 2016).
colon carcinoma (34 papers, 2016 to 2025). "The evaluation of mutations and the methylation of the AIM2 gene showed that it had a high percentage of single nucleotide variants (SNVs) and low methylation levels in colon cancer." (PMID 40002808, 2025). "In colon cancer, decreased expression of AIM2 is known to be associated with advanced stages of cancer and tumor progression, while low AIM2 expression is considered to be indicative of poor prognosis." (PMID 35846123, 2022). "AIM2-deficient mice exhibited intestinal stem cells that were predisposed to uncontrolled proliferation, which made them prone to colon tumor development through independent inflammasome mechanisms." (PMID 34571825, 2021). "This corroborates another study that has reported that AIM2 protein acts independently of the inflammasome and IL-1β in colitis-associated colon cancer." (PMID 29216217, 2017). "In support, in a mouse model of colitis-associated colon cancer (CAC) the genetic loss of AIM2 was associated with the activation of the DNA-dependent protein kinase (DNA-PK), a PI3K-related family member, which in turn promoted Akt phosphorylation and activation with an ensuing high tumor burden." (PMID 40002808, 2025). "Thus mutation inactivating AIM2 functions has been more frequently associated with colon cancer in humans." (PMID 33643304, 2020). "AIM2 was originally regarded as a tumour suppressor because its inactivation or mutation was found in a variety of tumours, including endometrial, gastric, and colon cancers, but it was found to be overexpressed in oral, nasopharyngeal, and non-small-cell lung cancer." (PMID 33828074, 2021). "The AIM2 activation was associated with an increased anti-tumor response after the anti-Programmed Cell Death 1 (PD-1) blockade, an effect that was attenuated in AIM2 knockout mice with colon cancer." (PMID 40002808, 2025). "(2015) investigated AIM2 involvement in inhibition of colon cancer by limiting the intestinal stem cell proliferation and controlling gut microbiome." (PMID 40692785, 2025). "Several pieces of scientific evidence have reported the ability of the AIM2 inflammasome to suppress colon cancer establishment and progression." (PMID 40002808, 2025). "It has to be pointed out that, according to the well-known inverse correlation between gene expression and DNA methylation, the reduced methylation levels of the AIM2 gene seems to be in contrast with the low AIM2 gene expression in colon cancer." (PMID 40002808, 2025). "As observed for colon cancer, the expression of AIM2 is low in BC samples according to The Cancer Genome Atlas (TCGA) and The Genotype-Tissue Expression (GTEx) databases." (PMID 40002808, 2025). "Collectively, these studies provide insights into the anti-tumor activity of AIM2 in colon cancer and CRC, paving the way for further investigation into therapeutic strategies targeting AIM2 in colon cancer and CRC patients." (PMID 40002808, 2025). "On the other hand, AIM2 suppresses colon carcinoma by binding to and inhibiting DNA-PK and downstream AKT signaling events needed for colon epithelial cell transformation." (PMID 37081890, 2023). "Summarily, our evidence suggests that AIM2 plays a critical role in impeding both the proliferation and metastasis of colon cancer in vivo." (PMID 37932362, 2023). "In order to substantiate the role of AIM2 in colon cancer, we utilized both the subcutaneous xenograft model and the lung metastasis model." (PMID 37932362, 2023). "In the early stage, sequencing results showed that the coding region of AIM2 gene with a high frequency of frameshift and missense mutations in primary high-level microsatellite instability (MSI-H) colon cancers and cell lines." (PMID 36118867, 2022). "Studies have shown that AIM2 is related to the occurrence and development of various tumors such as colon cancer, prostate cancer, and breast cancer." (PMID 36569221, 2022).